GDF6 (growth differentiation factor 6)
Diseases named in the same sentence as GDF6 in open-access papers (continued):
Sharing a sentence is not in itself a finding about the gene and the disease.
cancer (7 papers, 2017 to 2025). A tumor composed of atypical neoplastic, often pleomorphic cells that invade other tissues. "Further analysis revealed that in tumors with high GDF6 expression, the infiltration of the following cells was significantly increased: myeloid derived suppressor cells, hematopoietic stem cells, cancer associated fibroblasts, and endothelial cells." (PMID 40699648, 2025). "This cross-cancer association suggests that GDF6 can serve as a biomarker for dynamically monitoring tumor progression." (PMID 40699648, 2025). "Additionally, GDF6 reshaped the immune microenvironment by recruiting myeloid-derived suppressor cells (MDSCs) and cancer-associated fibroblasts." (PMID 40699648, 2025). "To further elucidate the role of GDF6 in cancer heterogeneity, we analyzed its expression differences across molecular subtypes, selecting BRCA, GBM, UCEC, and COADREAD as representatives due to their well-defined molecular classifications." (PMID 40699648, 2025). "Based on the UCSC pan-cancer dataset, Pearson correlation analysis revealed that GDF6 expression was positively correlated with marker genes of five immune pathways (chemokines, receptors, MHC, immune inhibitors, and immune stimulators)." (PMID 40699648, 2025). "GDF6 exhibited bidirectional expression patterns, with downregulation in 23 cancers (e.g., GBM, BRCA) and upregulation in 7 malignancies (e.g., KIRC, PAAD)." (PMID 40699648, 2025). "This study investigates GDF6’s context-dependent functions through pan-cancer multi-omics integration and functional validation." (PMID 40699648, 2025). "Transcriptomic data from TCGA (33 cancers, n = 10,535) and GTEx were analyzed to assess GDF6 dysregulation." (PMID 40699648, 2025). "GDF6 exhibits bidirectional dysregulation: downregulation in 23 cancers (e.g., GBM, BRCA) and upregulation in 7 subtypes (e.g., KIRC, PAAD), correlating with advanced stages (KIRP, STAD) and poor survival (OS/DFS in KIRP, STAD, MESO)." (PMID 40699648, 2025). "This pan-cancer analysis reveals GDF6 as a dual-function regulator with tissue-specific roles in tumorigenesis." (PMID 40699648, 2025). "The results showed that in 11 types of tumors, GDF6 expression exhibited significant stage-dependent differences, and the regulatory direction was cancer-specific." (PMID 40699648, 2025). "These IHC data provide critical evidence for the bidirectional expression of GDF6 at the protein level, corroborating the mRNA expression patterns observed in this study and reinforcing its context-dependent roles in cancer." (PMID 40699648, 2025). "To systematically evaluate the role of GDF6 in cancer progression, we first integrated TCGA pan-cancer data (33 cancers, n = 10,535) to analyze the correlation between its expression and pathological stage." (PMID 40699648, 2025). "Next, we integrated TCGA pan-cancer data (33 cancer types, n = 10,535 tumors) with GTEx normal samples to assess dysregulation of GDF6 in malignancies." (PMID 40699648, 2025). "GDF6 exhibits significant expression differences across cancer molecular subtypes, particularly pronounced in subtypes characterized by genomic instability." (PMID 40699648, 2025). "In this study, we found that GDF6 plays a multifaceted role in tumor progression through cancer-specific immune regulation, stemness remodeling, and microenvironment interaction networks." (PMID 40699648, 2025). "In this study, we systematically explored the complex roles of GDF6 in tumor progression, immune microenvironment regulation, and treatment response by integrating pan-cancer multi-omics data and functional experiments." (PMID 40699648, 2025). "This duality positions GDF6 at the nexus of tumor-immune crosstalk, yet its pan-cancer clinical implications remain unexplored." (PMID 40699648, 2025). "To further explore the mechanisms underlying the role of GDF6 in cancer development, we used GEPIA2 to identify the top 100 genes that are significantly co-expressed with GDF6." (PMID 40699648, 2025).
cancer (continued). "GDF6 upregulates the VEGFR/PI3K-Akt pathway, enhancing endothelial cell recruitment and vascularization, and collaborates with HIF-1α to regulate hypoxia responses and recruit cancer-associated fibroblasts (CAFs), fostering an immunosuppressive niche." (PMID 40699648, 2025). "Our pan-cancer analysis reveals GDF6’s unique capacity to stratify these opposing responses; high GDF6 expression associates with anti-PD1 refractoriness but potentiates anti-PD-L1 efficacy, likely through differential modulation of myeloid suppressive cells and antigen presentation machinery." (PMID 40699648, 2025). "In this study, we found that the expression pattern of GDF6 is significantly cancer-type-dependent." (PMID 40699648, 2025). "Interestingly, the most significantly upregulated genes in Ppm1dT/+ AML (Zbed3, Runx3, Marcks, Extl3, Pcbp4, Igf2bp3, Plch1, and Gdf6) were previously associated with AML and cancer progression." (PMID 37709843, 2023). "Growth differentiation factor 6 (GDF6), a member of the TGF-β superfamily, plays multifaceted roles in tumorigenesis, yet its molecular mechanisms and cancer-type-specific regulatory networks remain poorly defined." (PMID 40699648, 2025). "In combination therapy, for GDF6-high-expressing tumors, the combination of MDSC inhibitors (such as SX-682) or PARP inhibitors (in HRD-positive cancer types) may reverse immune suppression." (PMID 40699648, 2025).
tumor (6 papers, 2019 to 2025). "Furthermore, based on the tumor stemness index evaluated by methylation characteristics, GDF6 was significantly associated with stemness features in 13 types of tumors." (PMID 40699648, 2025). "As a member of the TGF-β superfamily, GDF6 exerts pleiotropic effects on tumor progression by regulating the immune microenvironment, genomic stability, and multiple signaling pathway networks." (PMID 40699648, 2025). "The scratch assay revealed that silencing GDF6 inhibited cell migration, supporting its role in promoting tumor invasion." (PMID 40699648, 2025). "Despite limitations in bulk omics data, this study positions GDF6 as a pivotal orchestrator of tumor progression, immune modulation, and therapy resistance." (PMID 40699648, 2025). "In gastric cancer, GDF6 overexpression correlates with tumor cell stemness, whereas in renal cell carcinoma, it paradoxically enhances VEGF-mediated vascular normalization." (PMID 40699648, 2025). "By integrating molecular biology, immunology, and clinical medicine across disciplines, GDF6 holds promise as a new target for tumor individualized treatment, propelling the development of precision oncology." (PMID 40699648, 2025). "Analysis of GDF6 in relation to three RNA modification-associated genes (m1A, m5C, and m6A) revealed a significant positive correlation with the expression of m6A regulators, suggesting that the epigenetic regulatory network may drive tumor progression by affecting GDF6 function." (PMID 40699648, 2025). "To explore the impact of GDF6 on tumor genomic stability, we assessed its correlation with TMB, MSI, and HRD." (PMID 40699648, 2025). "Validation in the EMT6 tumor model (TISMO database) confirmed that GDF6 expression increased in responders following anti-PD-L1 treatment." (PMID 40699648, 2025). "These subtypes are often associated with aggressive behavior and poor prognosis, suggesting that GDF6 may promote angiogenesis and tumor progression by activating the PI3K-Akt and VEGF pathways." (PMID 40699648, 2025). "Subsequently, we observed the correlation between GDF6 and tumor immune infiltration." (PMID 40699648, 2025). "Furthermore, we validated through IHC experiments that the expression of P2RY14 and GDF6 was decreased in tumor tissues." (PMID 39440060, 2024). "Notably, our survival analyses were based on univariate Cox models without adjustment for clinical covariates (e.g., tumor stage or treatment history), which limits causal interpretation of GDF6’s prognostic role." (PMID 40699648, 2025). "GDF6 may synergistically promote tumor immune suppression through these pathways." (PMID 40699648, 2025). "GDF6 expression increased with pathological grade in KIRP, BRCA, UCEC, and STAD, while it decreased with higher tumor grade in KIRC." (PMID 40699648, 2025). "In the “tumor only” setting, the most differentially upregulated genes in EVP were related to its paracrine function such as Gdf6, a member of the TGFβa agonist, Wnt16, epiregulin, and neuroregulin." (PMID 30604758, 2019). "In the metastasis-associated neoplastic cell states, we detected robust expression of neural crest (ZIC1, OLIG3), mesenchymal (MSX2, GDF6), and metastasis-related (DKK2) genes in addition to adrenergic genes (e.g., PHOX2B) that were shared with primary tumor cell states." (PMID 41279557, 2025). "Moreover, the investigation of protein expression levels of GDF6 and P2RY14 in OV and non-tumor tissues was conducted through the utilization of immune histochemistry (IHC) on the tissue microarray." (PMID 39440060, 2024).
adenocarcinoma (1 paper, 2022). A common cancer characterized by the presence of malignant glandular cells. "Loss of each regulatory interaction results in adenocarcinomas suggesting that regulation serves to prevent a GDF6 or TGFB2 promitotic signal from impacting the colon or endometrium, respectively." (PMID 36214621, 2022).
autosomal dominant disease (1 paper, 2018). Autosomal dominant form of disease. "Microduplication of chromosome 8q22.1 is mainly associated to Leri's pleonosteosis syndrome phenotype, an extremely rare autosomal dominant disease encompassing the GDF6 and SDC2 genes." (PMID 30123278, 2018).
congenital kidney malformations (1 paper, 2020). "By adding three patients with renal anomalies to the two patients previously reported, a total of 5 of 86 (5.8%) individuals carrying rare GDF6 variants described here and in the literature are known to be affected by congenital kidney malformations." (PMID 32737436, 2020).
connective tissue disorder (1 paper, 2024). A disease involving the connective tissue. "Of the patients without connective tissue disorder-associated symptoms, there was evidence of potential linkage with areas including the GDF3 and GDF6 genes, which encode for growth differentiation factors implicated in Klippel–Feil syndrome, found in 3–5% of the CM1 patients." (PMID 39458107, 2024).
neurodegenerative disease (1 paper, 2014). A disorder of the central nervous system characterized by gradual and progressive loss of neural tissue and neurologic function. "These conclusions synergize with past findings to argue for further analysis of GDF6 and other BMP genes as modifier loci, potentially affecting susceptibility to ALS and perhaps a broader suite of neurodegenerative diseases." (PMID 24586579, 2014). "The data also synergize to argue for further analysis of GDF6 and other BMP genes as modifier loci, affecting susceptibility to ALS and perhaps a broader suite of neurodegenerative diseases." (PMID 24586579, 2014).
neuromuscular disease (1 paper, 2014). "Furthermore, progression of neuromuscular disease in ALS model zebrafish was accelerated when this homologue of GDF6 was mutated: older zebrafish expressing mutant SOD1 exhibit ALS-like symptoms, but young fish only exhibited significant ALS-like neuromuscular deficits when on a gdf6a−/− background." (PMID 24586579, 2014). "This encouraged us to explore a potential role for gdf6a in neuromuscular degeneration, which would potentially implicate BMP/GDF6 genes as candidate loci in neuromuscular disease." (PMID 24586579, 2014).
GDF6 also shares sentences with these, for which no sentence is quoted: osteoarthritis (3 papers); thyroid cancer (3); liver cancer (2); myocardial infarction (2); adrenocortical carcinoma (1); ankylosing spondylitis (1); brachydactyly (1); carcinoid (1); cardiac disease (1); cardiac ischemia (1); Chiari malformation (1); Chiari type I malformation (1); chondrodysplasia (1); chronic kidney disease (1); congenital malformation syndrome (1); dysostosis (1); fibrodysplasia ossificans progressiva (1); fibrosis (1); gastric adenocarcinoma (1); glioblastoma (1); glioma (1); Glomerular sclerosis (1); head and neck squamous cell carcinoma (1); heart failure (1); hepatocellular carcinoma (1); hereditary retinal dystrophy (1); hypertrophy (1); infection (1); intervertebral disc degeneration (1); ischemia (1).
A further 29 diseases each share a sentence with GDF6 in 1 paper.